ERBB2 (erb-b2 receptor tyrosine kinase 2)
Diseases named in the same sentence as ERBB2 in open-access papers (continued):
Sharing a sentence is not in itself a finding about the gene and the disease.
cancer (continued). "The epidermal growth factor receptor (EGFR) family ErbB1 and ErbB2, stem cell factor (SCF)-KIT, and vascular endothelial growth factor receptor 3 (VEGFR3) pathways, major pathways related to cancer aggressiveness, were downregulated." (PMID 38886756, 2024). "To determine the accuracy and LOD of amplifications, we tested reference materials with known copy numbers across six cancer driver genes (EGFR, ERBB2, FGFR3 MET, MYC and MYCN)." (PMID 39682116, 2024). "Previously reported focal CNAs in MSS primary cancers included single-copy and double-copy gains involving CCND1, ERBB2, MYC and KLF5, and deletions of ARID1A, SMAD4 and APC7,31." (PMID 39112709, 2024). "We noticed that several cancer-related pathways were enriched, including JAK-STAT pathway, ERBB2 − EGFR and PI3K-AKT signaling." (PMID 39695095, 2024). "Taken together, several drugs that target ERBB2/HER2 and/or ERBB3/HER3, including small molecule inhibitors and antibodies, have shown evidence of pan-cancer activity in NRG1 fusion bearing malignancies." (PMID 38369520, 2024). "A population-wide examination of TT and LN single cells found that primary cancer overexpresses NOTCH2, NOTCH2NL, KIF5B, and ERBB4 but that metastatic cancer overexpresses CDK12, ERBB2, and CLDN11." (PMID 37322261, 2024). "In cancers such as NSCLC, EGFR and ERBB2 are highly co-expressed and approximately 10–15% of patients developing resistance to EGFR-targeted therapies exhibit ERBB2 mutations." (PMID 38713378, 2024). "We then compared amplifications around MYC, ERBB2 and EGFR in the whole chromosome view in corresponding highly amplified cancer tissues." (PMID 37298484, 2023). "Molecular characterization of CRC tumors has resulted in the identification of genetic alterations in cancer driver genes, such as KRAS, NRAS, BRAF, and ERBB2, which are now used to guide first‐line therapies." (PMID 37039257, 2023). "Our data show that adapter-tethered EGFR and ERBB2 fusions are capable of sustaining cancer cell growth and proliferation and, importantly, are sensitive to inhibition with EGFR and/or HER2 inhibitors." (PMID 37168365, 2023). "We here demonstrate that the CD19-4D5scFv fusion protein redirects the CD19-specific CAR T cells towards the ErbB2+ cancer cells and activates the CAR T cells to efficiently eliminate the CD19− ErbB2+ cancer cells in vitro and in a xenograft mouse model." (PMID 36672182, 2023). "These cancers all have in common epidermal growth factor (EGF) receptor overexpression/amplification, such as EGFR and ERBB2." (PMID 38041118, 2023). "Overall, we demonstrate that EGFR, ERBB2 and ERBB4 fusions are present across numerous cancer types and importantly are excellent candidates for targeted therapy development." (PMID 37168365, 2023). "The average gene alteration frequency was <2%, which is low compared to those of protooncogenes (i.e., MYC, ERBB2, RAS) that typically show sporadic gene amplification frequencies of > 20% in many cancers." (PMID 37268816, 2023). "In the case of HER2-positive BC brain metastasis, TKIs like lapatinib, a dual TKI that targets both EGFR and HER2/ErbB2, show great promise as cancer treatments." (PMID 37818447, 2023). "Remarkably, some receptors (ERBB2, ITGA3, and ITGB6) were mainly expressed in cancer cells, and their putative ligands (NRG1 and FN1) were over-expressed in CAFs." (PMID 37879219, 2023). "Upregulation of ErBb2 may either produce metastasis-related characteristics like angiogenesis or invasion, or it may promote curative resistance, ultimately deteriorating cancer cell metastasis and attempting distressing responses to cancer-curative MMP-9 and MMP-2 protein activities." (PMID 37845675, 2023).
cancer (continued). "Human epidermal growth factor receptor 2 (HER2, also known as ERBB2) proteins are overexpressed in a high proportion of GC cases and affect the maintenance of cancer stem cell subsets." (PMID 37386139, 2023). "On the contrary, some core kinases and transcription factors involved in cancer such as CDK6, ERBB2, JAK1, DAPK1, FOXO1, and RXRA were highly expressed in S-III." (PMID 38143770, 2023). "For each cancer type they are indicated in, EGFR and ERBB2 consistently rank the highest both in terms of the fraction of cell lines they are essential in and the mean and median p(dependency) across cell lines." (PMID 37835579, 2023). "For example, the MET oncogene can activate ERBB1 in some cancer cells and in others it is activated by ERBB1:ERBB2 heterodimers." (PMID 37669313, 2023). "This cohort study derived data on 184 patients from the phase 3 neoadjuvant Cancer and Leukemia Group B (CALGB) 40601 trial that enrolled patients with ERBB2/HER2-positive EBC in North America between January 1, 2008, and December 31, 2012." (PMID 38117494, 2023). "ERBB family fusions involving the EGFR, ERBB2 and ERBB4 genes are emerging therapeutic targets in several cancer types." (PMID 37168365, 2023). "According to bioinformatics prediction, ERBB2, SRC, TNF receptor, and AKT1 were predicted to be the key targets and play an essential role in cancer treatment." (PMID 36500678, 2022). "We investigated clinically relevant RTK fusion genes, namely ABL1, ALK, ERBB2, FGFR1-4, NTRK1-3, RET, and ROS1, because they are among the most frequent druggable cancer molecular biomarkers." (PMID 36009413, 2022). "Among newly identified genes, eleven other cancer targets were detected: MPL; ERBB4; VHL; FGFR3; KIT; KDR; PTEN; KRAS; PTPN11; ERBB2; and SMARCB1." (PMID 35621644, 2022). "There were no significant changes in gene expression levels for the seven other cancer genes (ABCC1, ALK1, BRCA1, DHRS2/HEP27, EGFR, ERBB2, and ERCC1)." (PMID 35743133, 2022). "On the other hand, SRC, CASP3, EGFR, ERBB2, mTOR, MMP9, and HIF1A followed the proteoglycans in cancer (degree 7)." (PMID 35959427, 2022). "Seven anti-HCC core targets (CASP3, EGFR, ERBB2, mTOR, MMP9, HIF1A, and PPARG) followed the pathways in cancer." (PMID 35959427, 2022). "In light of the clinical estimation of structural gene variation, we detected that higher ERBB2 mutations and more amplification are frequently associated with a worse prognosis of cancer, regardless of whether these cancers have more ERBB2 gene copy numbers or not." (PMID 36172165, 2022). "We propose a provocative paradigm shift in the field of growth factors in cancer progression, suggesting the administration of ERBB4 ligands, such as Neuregulin 4, as a strategy to improve the efficacy of anti-ERBB2 agents." (PMID 35664762, 2022). "We detected a novel ERBB2 extracellular domain VUS, c.1157A > G p.(E401G), in a cancer gene panel test." (PMID 34997908, 2022). "Several studies have shown that excessive accumulation of ERBB2 is one of the key triggers of abnormal excitation of the PI3K/Akt/mTOR signaling axis and is involved in the regulation of VM formation in cancer cells." (PMID 37304410, 2022). "Further analysis using bioinformatics prediction was performed to show that ERBB2, SRC, TNF receptor, and AKT1 are potential key targets and play an essential role in cancer treatment." (PMID 36500678, 2022). "On the other hand, SRC, CASP3, EGFR, ERBB2, mTOR, MMP9, and HIF1A followed the proteoglycans in cancer." (PMID 35959427, 2022). "As expected, prior targeted therapy, which was overwhelmingly EGFR-targeted, increased the proportion of cancers with BRAF V600E (12.6% vs. 6.5%, p = 0.019) and ERBB2 amplification (5.9% vs. 2.3%, p = 0.043)." (PMID 35621667, 2022).
cancer (continued). "These include unique cancer patient samples harboring EGFR E709K (n = 67), EGFR E928K (n = 1), ERBB2 E717K (n = 10), ERBB3 E925K (n = 7), ERBB4 E715K (n = 8), and ERBB4 E934K (n = 5) variants." (PMID 36860695, 2022). "The network results demonstrated that seven anti-HCC core targets (CASP3, EGFR, ERBB2, mTOR, MMP9, HIF1A, and PPARG) followed the pathways in cancer (degree 7)." (PMID 35959427, 2022). "Utilizing the patient datasets from Pan-Cancer (c-Bioportal), we observed a significant positive correlation between DDR1 expression and expression of genes BCR, EGFR, and ERBB2." (PMID 35664781, 2022). "EGFR family comprises four types of tyrosine kinase receptors, including ErbB1 (HER1), ErbB2 (HER2), ErbB3 (HER3), and ErbB4 (HER4), and it is highly expressed in cancer cells." (PMID 35565451, 2022). "Pan-cancer drug target RTK fusions also include the moieties of ALK, ERBB2, FGFR1-4, MET, RET, and ROS1 genes." (PMID 36009413, 2022). "Disease-free survival showed a correlation between ERBB2 enrichment and poor prognosis in CESE, LGG, LIHC, and PAAD cancer cases." (PMID 36172165, 2022). "Biomarkers of cancer such as overexpression of SDC1 and constitutive activation of ErbB2/HER2 were also identified." (PMID 36009225, 2022). "Many of these genes were transcription factors and several of them were known cancer genes (e.g., APC, BCL2, ERBB2, HRAS, TGFBR2)." (PMID 35008420, 2022). "ERBB family members including ERBB1/EGFR and ERBB2/HER2, are receptor tyrosine kinases that are often aberrantly activated leading to cancer cell migration, EMT, antitumor immunity and cancer cell survival." (PMID 35267943, 2022). "The human epidermal growth factor receptor 2 (HER2 or ERBB2) is a receptor tyrosine kinase, which is over-expressed in several types of human carcinomas." (PMID 36430176, 2022). "HPV integration is most frequently detected in genic regions, most often cancer-related genes, such as oncogenes (e.g., TP63, MYC, ERBB2) or tumor suppressor genes (e.g., BCL2, FANCC, HDAC2, RAD51B, CSMD1) and to a lesser extent in miRNA regions." (PMID 34439243, 2021). "Overexpression and/or amplification of ERBB2 and VEGF have been found in a variety of human cancers, including EC 12, 18, 19, 37-45." (PMID 34729115, 2021). "In our work, we constructed anti-ErbB2 and anti-IFN-β CrossMabs as a vehicle for endogenous and exogenous IFN-β for cancer treatment." (PMID 34944558, 2021). "ERBB2 (Erb-B2 receptor tyrosine kinase 2, also known as HER2) attracts a lot of attention in cancer research." (PMID 34765599, 2021). "It is worth highlighting the presence of predictive biomarkers for drugs that are currently in use for treating different cancers, such as PARP, ERBB2, EGFR, PIK3CA, mTOR, and Hedgehog signaling inhibitors." (PMID 34575676, 2021). "Previously, we reported that (E)-N-(5-benzylthiazol-2-yl)-3-(furan-2-yl) acrylamide (aminothiazole, ATZ-502) showed cytotoxic effects in several cancer cells by blocking the function of KPNB1 with pSTAT3, STAT3, EGFR, and ErbB2." (PMID 33801927, 2021). "In an analysis of 145 patients with ERBB2-amplified tumors sequenced prior to commencement of first-line anti-HER2 therapy, we found a significant (p = 0.01) reduction in the progression-free survival (PFS) of patients with MAPK-altered cancers." (PMID 34795269, 2021). "The advent of chimeric antigen receptors has made it possible to explore alternative targets for cancer therapy, especially in TNBC that lacks the common therapeutic targets ERBB2 and HR." (PMID 33670942, 2021). "Uptake of HB-Au-NPs was observed only in cancer cells that overexpressed EGFR and ErbB2 using photoacoustic microscopy." (PMID 34832857, 2021).
cancer (continued). "Most known cancer genes have been found through primary cytogenetic analyses, although sequencing of cancer genomes has revealed new cancer genes including BRAF, EGFR, ERBB2, PIK3CA, PPP2R1A, and JAK2." (PMID 34298667, 2021). "In the present study, we evaluate the prevalence of KDD in ERBB family members (EGFR/EGFR, ERBB2/HER2, ERBB3/HER3, and ERBB4/HER4) across multiple types of human cancers in order to refine our understanding of KDD as an oncogenic driver." (PMID 33654076, 2021). "Since resistance towards HER2 targeting can be expected, and since the major challenge in HER2 positive cancer is its highly invasive nature, an alternative approach would be to develop therapies that target the invasion-promoting functions of HER2/ErbB2." (PMID 33939112, 2021). "Here, we explore the effect of amplified cancer genes on ARE- mRNA pathways and found that ERBB2 is a significant mediator of perturbed activity in post-transcriptional control of gene expression." (PMID 34535639, 2021). "Studies in vitro showed that lapatinib inhibited the proliferation of ErbB2 and EGFR, which are overexpressed in cancer cells." (PMID 34944904, 2021). "HER2, also known as ERBB2, is a cell surface receptor tyrosine kinase of the ERBB family that is considered an oncogenic driver in many cancers, notably breast, ovarian and gastroesophageal cancers." (PMID 33959501, 2021). "Alternatively, ERBB2 may exert its predisposition to MPN acquisition by pathways that are not intrinsic or specific to hematopoietic cell signaling or development, such as genomic instability, inflammation, telomere biology, or other pathways implicated in cancer susceptibility." (PMID 34209587, 2021). "ERBB2 (HER2) amplifications represent a clinical biomarker for HER2-inhibitor therapy, and many of the breakpoint patterns as observed in POG570 advanced cancers would conceivably have involved the primary cancer." (PMID 34788622, 2021). "The CTD2 data set had a total of 79 unique drugs with sensitivities across 351 cancer cell lines that involve 22 targets, such as EGFR, HDAC1, MTOR, MET, ERBB2, and BRAF." (PMID 33795761, 2021). "Human epidermal growth factor receptor 2 (HER2, also known as ERBB2) is a cancer driver gene, and 1.7–3% of NSCLC patients harbor HER2 mutations." (PMID 34026634, 2021). "In solid tumors, usually, it is more common to recognize a tumor-associated antigen (TAA) wherever the expression of markers, such as CEA, ERBB2, EGFR, GD2, mesothelin, MUC1, and PSMA, is increased on cancer cells." (PMID 33494834, 2021). "CYT-low COAD tumors contained significantly more cancer genes harbored within chromothriptic regions (TCF12, NF1, ERBB2, JUN, JAK1 and BCL10)." (PMID 34316699, 2021). "This chromosomal region contains several genes connected to cancers including EME1, BRCA1, ERBB2, NF1, RAD51C, BRIP1, BIRC5 and PPM1D." (PMID 34885154, 2021). "They corresponded to cell fate determination, cell cycle activation, epigenetic modifications, DNA damage response, as well as cancer-related pathways including Wnt/β-catenin, PI3K/AKT/mTOR, Slit2/Robo1, MYC, and ErbB2-ErbB3 axes." (PMID 33747361, 2021). "Especially, they significantly decreased VEGFA, phosphorylated erythroblastic oncogene B-2 gene (p-ERBB2), p-AKT and p-VEGFR at the dose of 300 and 400 μg/mL, suggesting that anti-cancer effects were improved with increased dosages." (PMID 33801741, 2021). "EGFR (also known as ErbB1 and HER1), ERBB2 (HER2/neu and HER2), ERBB3 (HER3), and ERBB4 (HER4), members of the (EGFR)/(ERBB) family, are known among the most important cancer molecular targets." (PMID 34803458, 2021). "In line with this, the cBioPortal database OncoPrint analysis shows that most of these RTKs have the highest alteration rate, such as EGFR = 10%, ERBB2 = 7%, BRAF = 7%, ROS1 = 5%, and MET = 3%, in 165 (44,752 patients/46,632 samples) cancer cohort studies." (PMID 34769090, 2021).
cancer (continued). "PC cells express the proto-oncogene ErBB2, as well as type III mutant EGFR, designated EGFRvIII, which mediates the cell growth of several human cancer cells." (PMID 34064004, 2021). "Amplification of MDM2, ERBB2, CCND1, andCCNE1 and deletion of CDKN2A, PTEN, and RB1, whose alterations are all frequently found inbladder cancer, were also identified." (PMID 39703905, 2021). "We detected three frequently (>5%) altered genes (ATM, ERBB2 and PIK3CA) for which targeted therapies are available in other cancer types." (PMID 34771420, 2021). "The cytotoxic effect of ATZ-502 was demonstrated in several cancer cells by blocking the nuclear translocation of pSTAT3, STAT3, EGFR, and ErbB2 by karyopherin β1." (PMID 33801927, 2021). "ERBB2, EGFR and KRAS have FDA-approved drugs for use in cancer therapy, whereas CDKN2A has biological evidence for targetability, but associated drugs are not yet standard-of-care." (PMID 34298611, 2021). "Several known potent oncogenes that regulate CDKN2B-AS1 expression in various cancers have been reported in the literature, including MYC, RELA, and ERBB2." (PMID 33849428, 2021). "Ectopic expression of miR-375 significantly suppressed the expression of ERBB2 and subsequently downregulated one of its target genes, vascular endothelial growth factor A (VEGFA), which is related to cancer invasion and metastasis." (PMID 34729115, 2021). "CNAs of kinases, including ERBB2, FGFR1, and EGFR, were correlated with overexpressed proteins in substantial fractions of the same cancer types." (PMID 34552204, 2021). "Copy number amplification events in CCND1, CCND3, CDK6, ERBB2, FGFR1, MET, and PIK3CA also showed higher expression compared to wild types across various cancer types." (PMID 34429404, 2021). "The genomic identification of significant targets in cancer analyses (GISTIC) led to identify recurrent focal deletions (3p14.2 (FHIT), 11q11, and 4q13.2) and focal amplifications (17q13 (ERBB2), 8q24.21 (MYC), 3q26.31 (PIK3CA, TRAIL), 8q24.22, 8q21.13)." (PMID 32647357, 2020). "After adjusting for income quintile, ER status, ERBB2 status, and age, grade III cancers were more likely than grade I cancers to be IBC than SBC (odds ratio [OR], 6.33; 95% CI; 3.73-10.75)." (PMID 32975573, 2020). "The surface protein ERBB2, epidermal growth factor receptor 2 (HER2) is a member of the tyrosine kinase receptors family and is highly expressed by many cancer cells." (PMID 33101285, 2020). "Looking at each sub analysis, enrichment of miRNAs and mRNA fragments among the 88 significant RNAs in all TGCTs revealed several cancer related pathways, including mTOR, MAPK and ErbB2." (PMID 33251139, 2020). "Increased signaling through alternative EGFR family members ERBB2 and ERBB3 has previously been recognized as resistance mechanisms in different types of cancer including NSCLC (65, –67)." (PMID 32234966, 2020). "Human epidermal growth factor receptor-2 (HER2; ERBB2) plays an important role on signal transduction, proliferation, differentiation, invasion, and metastasis of cancer cells." (PMID 32974199, 2020). "ErbB-2 (or HER2) is a protein kinase with oncogenic properties, and an attractive candidate antigen for targeted TCR-based cancer immunotherapy." (PMID 33322601, 2020). "All anti-cancer activities are given by activation or inhibition of pathways such as HDAC1/PTEN/Akt, EGFR/ErbB2/ErbB3, and PI3K/Akt; PI3K-AK-mTOR, HDAC1/PTEN/Akt; Wnt/β-catenin." (PMID 32923398, 2020). "The results of interactive network analysis provide new perspectives on the role of hub genes, along with RYR2, ERBB2, PIK3CA, and HELZ2, with respect to the development of GC by querying multidimensional cancer genomics data in cBioPortal." (PMID 32801999, 2020). "Among these significant gene sets were several cell-signaling pathways, including the ERBB3 pathway, the PI3K/AKT signaling in cancer pathway and a pathway related to GRB7 events in ERBB2 signaling." (PMID 33154357, 2020).